MMP9 (matrix metallopeptidase 9)
Diseases named in the same sentence as MMP9 in open-access papers (continued):
Sharing a sentence is not in itself a finding about the gene and the disease.
ischemia (continued). "Numerous studies identify a role for MMP-9 in the mechanisms of compromise of the BBB, epileptogenesis or synaptic remodeling after ischemia or TBI." (PMID 22507553, 2012). "Levels of MMP-2 and MMP-9 are significantly elevated following ischemia, brain injury, and kainate treatment, implying a role for MMP-2 and MMP-9 in remodeling of neural circuits in response to neural activity and brain damages." (PMID 22567285, 2012). "In addition, we found that fasudil could significantly inhibit MMP9 expression induced by ischemia." (PMID 21541054, 2011). "One to 2 days after ischemia, the severe and late opening of the BBB correlates with increased MMP-9." (PMID 21040547, 2010). "For MMP-9, the duration of ischemia and the brain hemisphere (ischemic vs. non-ischemic) contributed most to the total variation in expression observed in these studies, followed by r-tPA treatment." (PMID 39273389, 2024). "We also investigated whether cell/PEMF treatment affected the expression of the inflammatory intermediaries MMP-9, TNF-α, and IFN-γ in the mouse ischemia model." (PMID 35163096, 2022). "In addition, many proteins potentially involved, like CD44 or matrix metalloproteinase 9 (MMP9), up-regulated in response to ischemia and decreased after CACs administration, were identified by a quantitative proteomics approach." (PMID 34572333, 2021). "While carnosine significantly reduced MMP-2 activity post-ischemia in rat brain homogenates, there was no statistically significant reduction in MMP-9 activity." (PMID 34299128, 2021). "The activity of MMP9 and MMP2 can break down the BBB via directly degrading tight junction proteins such as occludin and claudin-5, leading to reversible degradation early after the onset of ischemia and initiating vasogenic edema." (PMID 32221863, 2021). "As we did not record the changes in the level of the MMP-9 and c-Fos proteins in subcortical structures during ischemia and Semax treatment, we were not able to illustrate the spectrum of signaling pathways associated with these proteins." (PMID 34201112, 2021). "Moreover, morin suppressed MMP-9 expression, which improved BBB disruption by reducing TJ protein degradation and BBB permeability at pre-ischemia, during ischemia, and during reperfusion." (PMID 32770144, 2020). "Brain infiltrating monocytes up-regulate CD147, while resident microglia show increased MMP-9 activity but no up-regulation of CD147 acutely following ischemia." (PMID 32191628, 2020). "Brain injury-induced MMP-9 upregulation contributed to BBB leakage, but MSC transplanted lowered the MMP-9 transplanted and function which inhibited the critical BBB breakdown after ischemia (p < 0.05)." (PMID 29724240, 2018). "Lipopolysaccharide-induced and ischemia-reperfusion-mediated ALI in rodents have revealed pharmacologic inhibition of Src phosphorylation by Src inhibitors suppressed neutrophil influx, upregulated MMP-9 mRNA expression, and MIP-2 production." (PMID 26377087, 2015). "At 72 hours, no increased in MMP-9 intensity was observed in the supernatant of PMNs submitted in vivo to ischemia/reperfusion or ischemia/reperfusion and G-CSF treatment.In the brains of control animals there was no expression of MMP-9 at 24 and 72 hours." (PMID 24885160, 2014). "In MMP-9 knockout mice VEGF administration or hindlimb ischemia failed to induce progenitor cell mobilization." (PMID 23383236, 2013). "MMP-9 up-regulation was detected as early as 6 hours in GCL, clearly co-localized with RGC, but other sources of MMP-9, such as astrocytes, and infiltrating microglia, and neutrophils are present in ischemia." (PMID 23118988, 2012). "MMP-9 is not expressed in the CNS but seems to invade the brain together with leukocyte infiltration induced by focal ischemia." (PMID 22082476, 2011). "MMP-9 activity was highly variable following ischemia in this model and others when t-PA is not given." (PMID 22177314, 2011).
ischemia (continued). "In a cerebral-ischemic animal model, ischemia and organ culture were demonstrated to induce the activation of p38, ERK 1/2 and SAPK/JNK in cerebral arteries and the expression of inflammatory and MMP9 genes in the wall of cerebral arteries." (PMID 19272185, 2009). "As a neuroprotectant, UA can also suppress ischemia-induced inflammatory reactions, attenuate vascular impairment, preserve the integrity of the BBB, and decrease the infarct area by limiting the generation of reactive oxygen species on the blood vessel walls and decreasing MMP-9 activity." (PMID 39119562, 2024). "The correlation between the increased level of BMP-2 and high levels of MMP-9 and hCRP observed on Days 1 and 7 after MI, as well as at the six-month follow-up, most likely indicates that BMP-2 is an active driver of the myocardium inflammation under ischemia conditions." (PMID 32992577, 2020). "In addition, we found that treatment with zoledronate downregulated VEGF, eNOS, Akt, and MMP-9 activities in ischemic tissues, resulted in reduced numbers EPC-like cells in bone marrow, and inhibited the mobilization of EPCs in response to acute ischemia." (PMID 22848429, 2012). "However, administration of U0126 beginning 12 hours after reperfusion did not significantly reduce the ischemia-induced expression of MMP-9 or TIMP-1 in the cerebral vessel smooth muscle cells." (PMID 19497125, 2009). "In addition, neutrophil adhesion is not necessary for the increase in activation of MMP-9 after ischemia." (PMID 16078993, 2005). "Our group constructed a hypoxia response element-regulated MMP-9 vector to confine MMP-9 expression only in the hypoxic region; this vector promoted behavioral recovery after ischemia without aggravating BBB damage in the subacute phase of ischemia." (PMID 35743941, 2022).
cervical carcinoma (155 papers, 2002 to 2025). A carcinoma arising from either the exocervical squamous epithelium or the endocervical glandular epithelium. "Concentrations of MMP-2 and MMP-9 correlate with the FIGO stage and are associated with poor prognosis in endometrial cancer, whereas in cervical cancer, MMP-9 has been associated with a better outcome." (PMID 36982551, 2023). "MMP-2, which belongs to the same gelatinase family as MMP-9, is also highly associated with various tumor entities such as prostate cancer, gastrointestinal carcinomas, and cervical cancer." (PMID 34055644, 2021). "Our findings indicate that the proinvasive activity of SEMA5A is associated with the induction of MMP-2 and MMP-9 in HeLa cervical cancer cells." (PMID 29977159, 2018). "The FR3 is also considered promising because it inhibits MMP-2 and MMP-9, enzymes that are closely linked to dissemination of a type of cancer considered highly invasive and highly expressed in cervical cancer." (PMID 29770331, 2018). "ZA also inhibited tumour growth in a murine model of cervical cancer, which correlated with reduced angiogenesis and decreased production of matrix metallopeptidase 9 by Mφs proximal to and associated with tumours." (PMID 28501938, 2017). "Recent evidence has suggested that the positive expression of matrix metalloproteinase-2 (MMP-2) and matrix metalloproteinase-9 (MMP-9) was associated with PTX3 expression in the regulation of human cervical cancer cell metastasis." (PMID 28489600, 2017). "ZBRK1 also acts on MMP9 promoter to reduce MMP9 expression and thus inhibits metastasis of cervical carcinoma, and loss of ZBRK1 expression was found to increase KAP1 expression and promote metastasis and invasion." (PMID 25749518, 2015). "For instance, the upregulation of MMP-2 and MMP-9 collagenases is associated with the invasion and metastasis of cervical uterine neoplasm." (PMID 24804928, 2014). "Poor prognosis in cervical cancer was also associated with higher expression of MMP-9." (PMID 36982551, 2023). "Moreover, both the high expression of MMP-2 and low MMP-9 expression in both tumor and stroma cells seem to be associated with poor prognosis in cervical cancer, as well as in several tumors." (PMID 37509428, 2023). "EMT of cervical cancer is associated with upregulation of MMP9." (PMID 36911370, 2023). "High expression of MMP-9 was associated with a favorable cervical cancer prognosis." (PMID 32669083, 2020). "In addition, MMP-2 and MMP-9 expression are associated with the progression of cervical cancer when exposed to low concentrations of arsenic trioxide and humic acid, and both of these proteins play important roles in cancer progression and remodeling of the ectocervix." (PMID 29267213, 2017). "In cervical cancer cell lines, LATS1 demonstrated an inhibitory effect on both the proliferation and invasion of cervical cancer cells, as predicted by the regulation of p27 and Matrix metalloproteinase-9 (MMP9)." (PMID 40699764, 2025). "The expression of proteins and mRNA of MMP-2 is significantly elevated in human cervical cancer, while the release of MMP-9 induces angiogenesis and metastasis of these tumor cells." (PMID 39364049, 2024). "Our results showed that CD163 + CD204 + M2-TAM via STAT3/NF-κB signaling pathways was strongly responsible for increasing protein factors of EMT and invasion (MMP9), reverberating in a worse prognosis scenario in patients with cervical cancer." (PMID 39061137, 2024). "Additional research data reveals a new understanding of how bergenin inhibits the growth of blood vessels in cervical carcinoma cells by affecting various proteins involved in blood vessel formation, such as Galectin-3 and MMP-9." (PMID 39834829, 2024). "Further analysis showed bergenin to be a potent-angiogenic agent by reducing key angiogenic proteins like Galectin 3 and MMP-9 (Matrix Metalloprotease 9) in cervical carcinoma cells." (PMID 38961106, 2024).
cervical carcinoma (continued). "miR-221/222 have been demonstrated to target the 3′ untranslated regions (UTR) of TIMP3 in cervical cancer and lead to an increase in the levels of MMP2 and MMP9, as well as the promotion of cell migration and invasion in cervical cancer." (PMID 38542164, 2024). "Resveratrol was found to inhibit the migration and invasion of human metastatic lung cancer A549 and cervical cancer Hela cells by suppressing NF‐κB and AP‐1‐mediated MMP‐9 expression." (PMID 38628201, 2024). "It has been demonstrated that HPV16-E6/E7 oncoproteins are involved in the regulation of gene expression of MMPs (MT1-MMP, MMP-2, and MMP-9) and the migration of CaSki and SiHa cervical cancer cells." (PMID 38612895, 2024). "This study for the first time provides deep insight into bergenin-mediated toxicity in cervical carcinoma cells and identifies and validates the potential targets of bergenin, especially Galectin 3 and MMP-9 along with proposing many new ones." (PMID 38961106, 2024). "sLZIP is elevated in cervical cancer and contributes to migration and invasion via the induction of matrix metalloproteinase (MMP)-9 and c-Jun expression." (PMID 39594816, 2024). "The increased expression of MMP9 changed the macrophage infiltration in the tumor microenvironment and affected prognosis of patients with cervical cancer." (PMID 36911370, 2023). "Increased MMP2 and MMP9 concentrations correlate with the stage of cervical cancer and the age of the patients." (PMID 36982551, 2023). "In the present study, TAMs were revealed to drive tumor angiogenesis and progression in a spontaneous model of cervical cancer through the production of MMP-9." (PMID 36911370, 2023). "Treatment with genistein also decreased migration of cervical cancer cells by increasing MMP-9 activity." (PMID 38201463, 2023). "Another study, also in cervical cancer cells, demonstrated the suppression of viability, motility, and invasion by decreasing the expression of MMP-9." (PMID 36829876, 2023). "Elevated concentrations of MMP-2 and MMP-9 were correlated with the FIGO stage and are associated with poor prognosis in endometrial cancer, whereas in cervical cancer, elevated concentrations of MMP-9 have been associated with a better outcome." (PMID 36982551, 2023). "In order to clarify one of the possible mechanisms by which A3K2A3 reduces cervical cancer cell migration, the levels of MMP-9 expression were investigated." (PMID 36829876, 2023). "This coactivator function of TRIM29 has been reported for MMP9 and p63, in non-small cell lung cancer and cervical cancer cells, respectively." (PMID 36690626, 2023). "Fibronectin has been shown to regulate MMP-2 and MMP-9 expression and activity in several cancers, including cervical cancer." (PMID 36982551, 2023). "By comparing with the RNA level in normal cervical epithelium, it was revealed that the expression level of MMP9 in cervical cancer was significantly different." (PMID 36911370, 2023). "For example, ZNF350 inhibits cervical cancer progression by directly binding to the MMP9 promoter region and inhibiting its transcription." (PMID 38049396, 2023). "NaB alone up-regulated MMP2, MMP7 and MMP9 expression, and promoted the migration and invasion of cervical cancer cells." (PMID 36338704, 2022). "The inhibition of the Erk signaling pathway restored the inhibiting role of solamargine which interfered with CXCL3 overexpression, in invasion, migration, and expressions of MMP-2 and MMP-9 in cervical cancer cells." (PMID 36345403, 2022). "And HK2 also promoted cell motility and distant metastasis by elevating fibronectin/MMP2/MMP9 in cervical cancer cells." (PMID 35953860, 2022). "Further studies demonstrated that this promotion of cell motility by HK2 was probably a result of it inducing FN1, MMP2 and MMP9 expression by activating Akt1 in cervical cancer cells." (PMID 34758823, 2021).
cervical carcinoma (continued). "All of these results demonstrate that stimulated HK2 expression induces Akt1 (p-Akt1), FN1, MMP2 and MMP9 expression in cervical cancer cells." (PMID 34758823, 2021). "All of these results further confirm that HK2 induces FN1, MMP2, and MMP9 expression by stimulating Akt1 (p-Akt1) in cervical cancer cells, subsequently enhancing cell motility." (PMID 34758823, 2021). "Induction of MMP‐9 expression by laminin in a human cervical cancer cell line and upregulation of MMP‐9 as well as coordinated expression of MMP‐2 and MMP‐14 by fibronectin in a human T lymphocyte cell line have been demonstrated." (PMID 33030286, 2020). "The level of Bcl-2, MMP-2, MMP-9, Fascin, and Erzin expression was significantly upregulated in cervical cancer cells with LGALS1 overexpression, while converse results were obtained in LGALS1 knockdown cancer cells." (PMID 32047564, 2020). "Pentraxin 3 (PTX3), a molecule involved in MMP expression, is a component of innate immunity whose knockdown inhibits MMP-2 and MMP-9, decreasing migration and invasion of cervical cancer cells in vitro and in vivo." (PMID 32455616, 2020). "In contrast, high expression of MMP-9 in the stroma (RR; 95%CI: 0.19; 0.05–0.65) and in the tumor (HR; 95%CI: 0.19; 0.04–0.90) had a protective effect on cervical cancer prognosis." (PMID 32669083, 2020). "E-cadherin down-regulation and MMP-9 up-regulation induced by Snail can further accelerate the invasion and migration of cervical cancer cells." (PMID 31956363, 2020). "The inhibition of MMP-9 expression in infiltrating macrophages through treatment with zoledronic acid effectively diminishes angiogenic responses in cervical cancer cells." (PMID 32972437, 2020). "MMP-9 belongs to the family of matrix metalloproteinases, and its expression is positively correlated with the invasive potential of cervical cancer." (PMID 31956363, 2020). "Another group showed that silencing of DEK led to downregulation of Wnt/β-catenin and MMP-9 in cervical cancer." (PMID 31766266, 2019). "Taken together, these results indicate that PLA can upregulate the expression of migration- and invasion-related MMPs in cervical cancer cells, particularly the expression of MMP-9." (PMID 31572058, 2019). "Previous studies have indicated that CREB3 can bind directly to the c-Jun promoter and subsequently enhance mmp9 activity in cervical cancer cells, which contributes to cervical cancer progression." (PMID 30940151, 2019). "PLA significantly promoted the migration and invasion of SiHa, HeLa, and C-33A cervical cancer cells as well as upregulated matrix metalloproteinase-9 (MMP-9) expression." (PMID 31572058, 2019). "Studies have shown lower levels of proteolytic activity for MMP-9 with use of indinavir, namely in cervical cancer." (PMID 31687607, 2019). "ZNF350 is also known to inhibit cervical carcinoma metastasis, perhaps via modulation of MMP9 and KAP1 expression." (PMID 30613364, 2018). "At the same time, suppression of lncRNA HOTAIR can reduce the proliferation, migration and invasion of cervical cancer cells and decrease the expressions of some metastasis-associated proteins (VEGF and MMP-9) and EMT-related proteins." (PMID 30518760, 2018). "Second, SEMA5A stimulates MMP-2 and MMP-9 to increase the invasive potential of cervical cancer cells." (PMID 29977159, 2018). "MMP-9 is also closely related to the metastasis of malignant tumors, so we studied the changes of MMP-9 in cervical cancer HeLa cells and Caski cells under the action of FA." (PMID 30013454, 2018). "One study investigated the expression of MMP-9 in cervical cancer specimens from 225 cases using immunochemistry assays." (PMID 30262739, 2018). "The inhibitory effect of FOXF2 on β-catenin, c-Myc, CyclinDl, MMP9, and Lgr5 will provide an important theoretical basis for the diagnosis and targetted therapy of cervical cancer." (PMID 30249755, 2018).